IL6 (interleukin 6)
Diseases named in the same sentence as IL6 in open-access papers (continued):
Sharing a sentence is not in itself a finding about the gene and the disease.
cancer (continued). "In our study, progression of metastasis was also associated with an increased concentration of IL-6, a major pro-inflammatory cytokine that affects cell proliferation, survival, and metabolism and is known to be associated with the progression of various types of cancer." (PMID 29788918, 2018). "IL-6 is a pro-inflammatory cytokine normally released by several cell types (e.g., monocytes, T cells, fibroblasts, epithelial and endothelial cells), and whose aberrant expression is associated with the growth, metastasis, and chemotherapeutic resistance in a wide range of cancers." (PMID 29296231, 2017). "Indeed, IL-6 expression in serum has been linked with poor prognosis in cancer patients." (PMID 27571063, 2016). "In addition to its role in inflammation, IL-6 is involved in numerous cellular processes and associated diseases including cardial infarction, renal disease, cognitive dysfunction, atherosclerosis, and cancer, to name just a few." (PMID 27129274, 2016). "We therefore utilized Mendelian randomization to assess whether the relevance between circulating IL-6 and cancer is causal by selecting the most frequently evaluated variant -174G/C in IL-6 gene as a genetic instrument to minimize residual confounding and reverse causation." (PMID 26096712, 2015). "However, it remains unclear whether the relevance between circulating IL-6 and cancer is causal as the issue of confounding or reverse causation is often unavoidable in observational epidemiology." (PMID 26096712, 2015). "Sixthly, only one variant in IL-6 gene was selected, and investigation on other candidate genes or polymorphisms involved in IL-6 regulation was highly encouraged, leaving a challengeable task to test whether this variant integrated with other risk determinants will enhance cancer risk prediction." (PMID 26096712, 2015). "Many inflammatory cytokines such as IFN-γ and IL-6 can also increase production of Jagged and/or decrease that of Delta hence possibly forming a positive feedback loop that rakes up N-J signaling and mediates chronic inflammation, a hallmark of cancer, in the stroma." (PMID 26258068, 2015). "In addition, lung cancer-associated EVs may contribute to cancer progression by triggering oncogenic signals with the IL-6 and VEGF cargos." (PMID 26082317, 2013). "However, adjustment by CRP attenuated the association between IL-6 and cancer mortality." (PMID 22514624, 2012). "However, there may be a more promising role for anti-IL-6 therapy in the management of cancer-related, inflammation-associated symptoms such as cachexia, fever, and pain." (PMID 24213115, 2011). "In spite of the increasing evidence that IL-6 and other pro-inflammatory cytokines may play a role in the pathophysiology of mood disorders and cause behavioural and neuroendocrine consequences, in cancer patients these phenomena are rather more complicated." (PMID 17288583, 2007). "For example, IL-6 inhibitors, such as tocilizumab, have shown efficacy in reducing cytokine-induced inflammation and improving outcomes in certain cancers." (PMID 41497141, 2026). "For example, MSTN inhibitors can effectively alleviate cancer cachexia symptoms, and the combination of anti-interleukin-6 treatment with immune checkpoint blockade therapy can produce a significant synergistic therapeutic effect." (PMID 42094205, 2026). "STAT3 is a key downstream regulator of IL-6, playing an essential role in adaptive growth and cancer development in PC." (PMID 41596531, 2026). "Macrophage-derived IL-6 subsequently activates the JAK2/STAT3 pathway in cancer cells, suppressing ENZ-induced apoptosis and conferring therapeutic resistance." (PMID 41990247, 2026).
cancer (continued). "In cancer-associated fibroblasts, acidic activation of GPR68 promotes IL-6 expression via a cAMP-PKA-CREB pathway." (PMID 41595528, 2026). "In cachectic cancer patients, inflammatory alterations (including increased IL-6 expression) have been reported more prominently on SAT than in visceral adipose tissue (VAT), supporting the concept of depot-specific immunometabolic remodeling." (PMID 41597384, 2026). "As a pleiotropic cytokine, IL‐6 performs multiple functions to boost the adaptability of cancer cells to conquer an unfavorable environment." (PMID 40968783, 2026). "Patients with elevated serum IL-6 levels had significantly lower 5-year cancer-specific survival (p < 0.005) and shorter progression-free survival (p < 0.001)." (PMID 41681886, 2026). "Multivariate Cox regression identified IL-6 (p = 0.018) was significant prognostic indicators for cancer patients." (PMID 41853712, 2026). "IL‐6 is well established as a mediator of inflammatory signaling and a promoter of stem cell‐like properties in multiple cancers, including GBM." (PMID 41556041, 2026). "Specifically, we observed a significant decrease in the levels of MIP-1α, GM-CSF, IL-13, IL-6, IL-10, IL-5, IL-12p70, and IL-4 after SNS administration, all of which are associated with the severity of MMD symptoms and cancer prognosis." (PMID 41491244, 2026). "Aside from its benefit to cancer cell survival and angiogenesis, IL‐6 also induces resistance to Cisplatin and Paclitaxel." (PMID 40968783, 2026). "The IL-6 signaling is widely recognized as a significant pathway to various cancers, including hematological malignancies." (PMID 41550719, 2026). "Interleukin-6 (IL-6), which mediates Rb phosphorylation, is elevated in cancer patients with high CRP and low Alb levels." (PMID 38965074, 2025). "Our research identified a positive correlation between blood IL-6 concentrations and IL-6 expression in cancer cells within HCC tissues." (PMID 40447887, 2025). "This aligns with the systemic inflammatory response observed in cancer, where chronic inflammation drives neutrophilia while simultaneously suppressing albumin synthesis via cytokine-mediated pathways (e.g., IL-6 and TNF-α)." (PMID 40709341, 2025). "The ECM and cancer cells reprogram resident immune cells, generating a pro-inflammatory environment promoted by cytokines like interleukin 6 (IL-6) and interleukin 8 (IL-8)." (PMID 39940673, 2025). "The present study investigated the contribution of CAFs to L-OHP resistance in CRC cells, with a focus on IL-6 secretion and its impact on cancer cell survival." (PMID 40718440, 2025). "Treatment with 1,25-(OH)2D3 exerts a significant inhibitory effect on the IL-6–JAK–STAT3 signaling pathway in cancer cells." (PMID 41246358, 2025). "Heterogeneity at post-intervention was moderate-to-high for CRP, IL-6, IL-6-CNS, IL-6-cancer, TNF-α, IL-10, IFN-γ, BDNF, and cortisol." (PMID 40281902, 2025). "In conclusion, the interplay between these inflammatory mediators—IL-6, IL-1β, TNF-α, CCL2, PGE2, GM-CSF, and bradykinin—highlights their collective role in the mechanisms underlying cancer pain." (PMID 40579593, 2025). "While IL-6 is known to promote wound healing, it has also been shown to have pro-tumorigenic effects by stimulating cancer cell proliferation, invasiveness, and metastasis." (PMID 40765592, 2025). "Faecalibacterium also regulates cancer cell proliferation and invasion by inhibiting the IL-6/STAT3 pathway." (PMID 40281554, 2025). "Chemotherapeutic agents (like docetaxel or paclitaxel) induce Il-6/IL-8 secretion with an expansion of cancer stem cells in triple negative breast cancer." (PMID 39859345, 2025). "For instance, TGF-β and IL-6 are recognized for their ability to stimulate cancer cell proliferation." (PMID 39934876, 2025). "Elevated levels of IL-6 and consequently enhanced IL-6/JAK/STAT signaling have been observed in cancers of the breast, prostate, kidneys, ovaries and pancreas." (PMID 40643463, 2025).
cancer (continued). "The myCAFs, characterised by high α-SMA expression and low IL-6 expression (α-SMAhighIL -6low) phenotype, were in close proximity to neoplastic cells, forming a structural ring surrounding clusters of cancer cells." (PMID 39780187, 2025). "At the same time, protective myocytic factors such as IGF-1 and IL-15 are downregulated, and the muscle response to exercise-induced myogenic IL-6 in cancer patients shifts from anti-inflammatory to pro-inflammatory characteristics." (PMID 41140691, 2025). "Numerous factors, such as co-cultivation with cancer cell ascites or exposure to IL-6, leukemia inhibitors, or purine adenosine, can polarize M2d macrophages (tumor-associated macrophages), which in turn promotes angiogenesis and cancer dissemination." (PMID 40599770, 2025). "The opposite trend was observed in MDSCs cocultured with USP25 overexpressing cancer cells, and the administration of IL-6 reversed this trend." (PMID 41326342, 2025). "Baicalin reduces anorexia by inhibiting cytokine expression (TNF-α and IL-6), prevents muscular atrophy by reducing MuRF1 and atrogin-1 expression, and inhibits NF-κB activation in a cancer cachexia model." (PMID 41011274, 2025). "Patients with elevated circulating IL-6 levels are known to have a poorer response to ICI therapy and cancer-related prognosis than those with normal IL-6 levels." (PMID 41019062, 2025). "In vivo, luteolin decreases TNF-α and IL-6 levels, suppresses muscle protein breakdown genes (MuRF1 and atrogin-1), and prevents cancer-induced muscle wasting." (PMID 41011274, 2025). "In the pathogenesis of cancer, elevated levels of IL6 activated the JAK/STAT signaling pathway, which is typically linked to a poor prognosis for patients." (PMID 40874680, 2025). "Interleukin-6 (IL-6) is a highly pro-inflammatory cytokine involved in the etiopathology of several inflammatory diseases and cancer." (PMID 38980514, 2025). "Clinically, IL-6 pathway activation, especially via the JAK/STAT pathway, is linked to aggressive cancer phenotypes and poor prognosis in ovarian, prostate, breast, and HNSCC patients." (PMID 39858048, 2025). "IL‐6 stimulates the growth of tumors by controlling various signaling pathways and cancer hallmarks, such as angiogenesis, invasiveness and metastasis, survival, proliferation, apoptosis, and especially, metabolism." (PMID 39803280, 2025). "A pivotal player in this network is IL-6, which activates the potent pro-oncogenic JAK/STAT3 pathway, a process linked to the expansion of cancer stem cells and therapeutic resistance." (PMID 41302515, 2025). "IL6 is a critical mediator that immediately orchestrates the alert response signals in emergencies, including cancer, by signaling through various immune cells, such as macrophages and monocytes, that patrol the body." (PMID 40427188, 2025). "Inflammatory cytokines such as NF-κB, IL-6, IL-1β, and TNF-α are indicators of inflammation and can be used to assess the severity of cancer-associated myocardial damage." (PMID 40182041, 2025). "IL-6, a pivotal regulator of inflammation, autoimmunity and cancer, predominantly exerts its function via the IL-6/STAT3 pathway." (PMID 41291543, 2025). "The underlying mechanisms of cancer cachexia are mainly involved in the up-regulation of inflammatory cytokines such as TNF-α and IL-6, which correlate with the imbalance between protein synthesis and protein degradation in muscle cells." (PMID 41226740, 2025). "IL6 is a central mediator that modulates the function and behavior of these immune cells, contributing to a pro-tumorigenic environment that facilitates cancer cell survival and dissemination." (PMID 40427188, 2025). "First, regarding cytokines in AF, the prognostic impact of inflammatory cytokines in patients with malignant tumors has been investigated in a study that reported the presence of IL-1β, IL-6, IL-8, IL-12, TNF-α, and IL-10 in AF." (PMID 39755760, 2025).
cancer (continued). "This leads to the production of a large amounts of IL-6 by TAMs, thereby promoting cancer progression." (PMID 40109347, 2025). "Genetic variations, particularly SNPs affecting MMP-9 and IL-6, have been linked to an increased risk of VTE, especially in cancer patients." (PMID 40299499, 2025). "CXCL5 neutralization ameliorated muscle wasting induced by CXCL5 and IL-6 co-treatment, and also prevented atrophy in cancer-activated CAF CM-treated human myotubes." (PMID 41392310, 2025). "Upon polarization to the M2 phenotype, TAMs secrete pro‐inflammatory factors like IL‐6, which further promote the growth and migration of cancer cells." (PMID 40391753, 2025). "Its abundant oxygen-containing surface groups facilitate bioreceptor immobilisation and electrochemical sensing, enabling recent biochar-based biosensors for clinical analytes such as interleukin-6 (IL-6) in inflammation and cancer monitoring." (PMID 41228776, 2025). "Chronic inflammation leads to the sustained release of pro-inflammatory cytokines such as TNF-α, IL-1β, and IL-6, together with chemokines, which collectively enhance cancer cell survival, proliferation, angiogenesis, and invasion." (PMID 41302515, 2025). "Targeting the IL-6/JAK/STAT3 pathway has emerged as a promising strategy to overcome CAF-mediated immune suppression in cancer." (PMID 40934009, 2025). "TNF-α, IL-6, and INF-γ have been implicated as mediators of the metabolic changes associated with cancer cachexia." (PMID 40430444, 2025). "In particular, IL-6 can suppress the function of NK cells, leading to a reduced ability to target and eliminate cancer cells." (PMID 40740773, 2025). "For cancer, TNFR1 mediated 43.2% of the positive association with IL-10, while there was slight evidence that IL-6 also mediated 13.2% of the association independently of TNFR1 (p = 0.130)." (PMID 41280118, 2025). "The study aimed to prospectively investigate the clinical value of interleukin-6, myeloperoxidase, and tumor necrosis factor alpha as potential biomarkers of cancer therapy-related cardiac dysfunction (CTRCD) in patients receiving anthracycline treatment." (PMID 40362309, 2025). "Among the pro-inflammatory cytokines, IL-1β, IL-6, and IL-12 showed the most robust differences, with IL-1β showing a maximum plasma concentration of 182 pg/mL in cancer patients, compared to 3 pg/mL in controls." (PMID 40612845, 2025). "Different cytokines, including TGFβ, IL6, and IL10, as well as cancer-associated metabolites, including tryptophan metabolites, lactate, and prostaglandin E2, inhibit cytotoxic cell functions at various levels." (PMID 40163355, 2025). "Regarding the betulin derivatives EB5 and ECH147, the SW1116 cancer cells consistently exhibited a reduction in IL-6 gene expression at all examined time points." (PMID 41256010, 2025). "Circulating and intratumoral cytokines increase rapidly during surgery with elevated levels of IL-6 and IL-1Ra in plasma, pleural fluid, and tissue studied as markers of surgical stress after thoracic surgery in patients with cancer." (PMID 40331601, 2025). "Cancer cell-derived IL-6 inhibited interleukin-12 subunit β (IL-12β) secretion and antigen presentation by dendritic cells, rendering them unable to activate cytotoxic CD8+ T cells." (PMID 40270603, 2025). "Future research should also investigate IL-6 as a key driver of cancer progression across multiple malignancies." (PMID 40944094, 2025). "The released IL-6 activates EMT signaling in cancer cells, enhancing their migratory and invasive capabilities." (PMID 41417432, 2025). "C-reactive protein (CRP) is released in response to pro-inflammatory cytokines like interleukin-6 (IL-6), and is often elevated in cancer patients, thus serving as a marker of inflammation." (PMID 39940314, 2025). "Adipose tissue is implicated as a key driver of development and progression of some cancers, in part by releasing pro-inflammatory cytokines such as IL6." (PMID 40961077, 2025).
cancer (continued). "The incorporation of delta‐He analysis amidst ongoing investigations into its relationship with hepcidin and inflammation, including IL‐6, suggests its potential as an unmet predictive and prognostic tool for patients with cancer." (PMID 40186416, 2025). "The stromal compartment, including cancer-associated fibroblasts (CAFs), releases transforming growth factor-β (TGF-β), interleukin-6 (IL-6), and vascular endothelial growth factor (VEGF)." (PMID 41153826, 2025). "This aligns with findings from a network meta-analysis in cancer patients showing that combined aerobic and resistance training was superior to single-modality exercise in reducing inflammatory markers such as IL-6, IL-8, IL-10, TNF-α, and CRP." (PMID 41583457, 2025). "In conjunction with our observed increase in macrophage SREBP1, there were simultaneous increases in Arg1, Cxcl5, and Il6, all of which can promote cancer progression in different cancers." (PMID 41462606, 2025). "A low concentration of TNF hinders the proliferation of some cancers, but a high concentration stimulates the production of IL-6 by stimulating monocytes, macrophages, lymphocytes, and neutrophils." (PMID 39802656, 2025). "A significant upregulation in IL-6 mRNA expression was particularly evident 24 h post-treatment with betulin in both the SW1116 cancer cells and the normal CCD-841 cell line." (PMID 41256010, 2025). "We have shown that the mechanism involved appears to be through cytokines such as EGF, PDGF, TNF-α, IFN-γ or IL-6, which activate signaling pathways within the cancer cells themselves that lead to FN1 production." (PMID 40096084, 2025). "Novel inflammatory indices (NLR, PLR, LMR) correlate strongly with traditional biomarkers (e.g., CRP, WBC, IL-6) and demonstrate prognostic value in the general population and cancer patients." (PMID 41280395, 2025). "The expression of TLR4 promotes the secretion of cancer‐promoting factors by macrophages, including IL‐6, IL‐23p23, and TNF‐α, enhancing inflammation and cancer growth." (PMID 40547943, 2025). "In our investigation, the mean serum IL-6 concentrations were significantly higher in the NB patients than in the non-cancer control group." (PMID 40722593, 2025). "They secrete numerous growth factors and cytokines, including TGF-β, FGF, PDGF, IL-6, and IL-8, which drive cancer cell proliferation." (PMID 40485724, 2025). "Regarding the relationship between M2 macrophages and IL-6, it is known that IL-6 is involved in the polarization of M0 macrophages to M2 macrophages in cancer cells of other organs." (PMID 39652104, 2025). "Previous studies have shown that blocking IL-6 increased anti-cancer NK cell activity in HCC cell cultures induced by CoCl2." (PMID 40430040, 2025). "Increased expression of matrix metalloproteinases and IL-6 were also noticeable; IL-6 in inducing an inflammatory microenvironment result in the end of the latency period and cancer cell proliferation and growth and was recently reviewed." (PMID 41373503, 2025). "The mechanisms by which IL-6 mediates cancer progression and resistance to therapy are poorly defined." (PMID 40317079, 2025). "Dysregulation and elevation of IL-6 have been suggested to play significant roles in the development of inflammatory and autoimmune disorders as well as cancer." (PMID 39781345, 2025). "Modulates EMT and IL-6-driven M2-type macrophage infiltration that promotes cancer progression and resistance to doxorubicin by modulating NF-κB signaling." (PMID 39936995, 2025). "DSCs emit IL‐6, which triggers the Stat3 and NF‐KB pathways and promotes the development of cancer cells." (PMID 41179371, 2025). "Macrophages and neutrophils primarily contribute to the synthesis of TNFα, which subsequently stimulates the production of other proinflammatory cytokines, including IL-6 and IL-1β, thus promoting cancer." (PMID 40869207, 2025). "IL-6 signaling is involved in several cellular processes, including inflammation, cell proliferation, and cancer." (PMID 40021961, 2025).